GOLGA6L22 (golgin A6 family like 22)
Tractability: No criterion of Open Targets' tractability assessment is met for any kind of drug.
Gene: Protein-coding gene on chromosome 15 (22,458,903 to 22,469,226, forward strand). Ensembl gene ENSG00000277865.
Genetic constraint (gnomAD): Loss-of-function variants: 14 observed, 12.14 expected, observed/expected ratio (o/e) 1.15, 90% interval 0.76 to 1.75. The upper end of that interval is the gene's LOEUF score, 1.75, which puts it in group 6 of 6, group 1 being the genes least tolerant of losing a copy. Missense variants: 79 observed, 106.88 expected, observed/expected ratio (o/e) 0.74, 90% interval 0.62 to 0.89. Synonymous variants: 17 observed, 22.83 expected, observed/expected ratio (o/e) 0.74, 90% interval 0.51 to 1.12.
Homologues: Paralogues in human: GOLGA6L24 (96% identical), GOLGA6L25 (95% identical), GOLGA6L6 (80% identical), GOLGA6L1 (73% identical), GOLGA6L26 (72% identical), GOLGA6L2 (39% identical), GOLGA6L7 (35% identical), GOLGA6L4 (17% identical), GOLGA6L10 (16% identical), GOLGA6L9 (15% identical).